EGFR (epidermal growth factor receptor)
Diseases named in the same sentence as EGFR in open-access papers (continued):
Sharing a sentence is not in itself a finding about the gene and the disease.
tumor (continued). "ILT4 inhibition prevented the immunosuppressive TME and tumor growth of EGFR-activated NSCLC both in vitro and in vivo." (PMID 33537094, 2021). "A small number of GBM cells within a tumor seem to express both wild-type EGFR and EGFRvIII mutant proteins." (PMID 34835657, 2021). "Immunohistochemical analysis illustrated that nearly half of the HCCs were EGFR-positive (15/31, 48.4%) and that EGFR positivity of the cell membrane in non-tumor liver tissue was inversely correlated with nuclear GR positivity (p = 0.0373)." (PMID 33806040, 2021). "Many clusters apparently had unequal cell distributions between EGFR-WT and EGFR-MT, indicating differences in the composition of tumor-infiltrating immune cells between the two molecular subtypes of NSCLC." (PMID 34663810, 2021). "Array CGH was performed for these four cases with the same mutation profiling among paired tumours by NGS and for three cases (Cases 3, 15 and 17) with the same driver mutations that included EGFR or KRAS mutations." (PMID 33707471, 2021). "On the other hand, other reports point toward a tumor suppressive role for BCA2 due to its effects on the down-regulation of the proto-oncogenes epidermal growth factor receptor (EGFR) and c-Myc." (PMID 34589482, 2021). "Compound 56 was evaluated as good antiproliferative EGFR-TK inhibitors against many tumor cell lines." (PMID 34443583, 2021). "Among these, variants in specific codons of the Kirsten RAS (KRAS) oncogene are of particular interest due to their ability to predict tumor response to anti-epidermal growth factor receptor (EGFR)-targeted therapies." (PMID 34640513, 2021). "The treatment of N1mAbs reduces tumor cell proliferation in vitro and in vivo, and sensitizes the cells to EGFR inhibitor, suggesting that NLRR1 is a novel regulatory molecule of RTK function." (PMID 34277416, 2021). "EGFR-labeled MSNs were also used as directional carriers of nano-contrast agents for real-time tumor detection." (PMID 34322025, 2021). "In this study, we show binding of a novel bispecific single domain antibody (VHH) to both CD16 (FcRγIII) on NK cells and the epidermal growth factor receptor (EGFR) on tumor cells of epithelial origin." (PMID 34771609, 2021). "In this study, we identified the sensitivity and HER2 positivity of the patient’s cancer on the basis of drug sensitivity of the vital tumor cells to EGFR-TKi in an ex vivo drug screen." (PMID 34604070, 2021). "Anti-EGFR Ab/FcBP-LGA-PEI miR-198 mimics NPs or HIV gp120 Ab/FcBP-LGA-PEI/miR-198 mimics NPs as the control randomly injected the tumor-bearing mouse through tail vein (n = 4 for each group)." (PMID 34577541, 2021). "HER2 hCART41BBζ or EGFR hCART41BBζ exhibit high levels of specific cytotoxicity directed at multiple tumor targets that express high and low antigen levels." (PMID 34290709, 2021). "Drawing insights into the functions of these genes, several tumor proliferation-related genes (EGFR, NOTCH1, and MAP2K1) and the anti-apoptosis related genes (BCL2L1, XIAP) were detected." (PMID 33637972, 2021). "Inhalation delivery resulted in significantly better survival of rats with the highly aggressive, EGFR mutant, H1975-derived lung tumors and the tumor burden of the moderately growing, KRAS mutant, A549-derived lung tumors." (PMID 33860729, 2021). "Compounds 2, 3, 8, 10, and 11 were tested as EGFR-TK inhibitors to demonstrate their possible anti-tumour mechanism compared to gefitinib (IC50= 0.90 μM)." (PMID 34227457, 2021). "The largest benefit of anti-EGFR was observed in patients with mesenchymal CMS4 tumours when combined with an irinotecan backbone." (PMID 34253874, 2021). "Some of the generated molecules were almost as potent and efficacious as therapeutic modality Cetuximab in triggering NK cell-mediated lysis of EGFR-overexpressing tumor cell line A431." (PMID 34759924, 2021).
tumor (continued). "The purpose of this study was to assess the predictive value of monitoring EGFR genomic alterations in circulating tumor DNA (ctDNA) from patients with NSCLC that undergo treatment with the third‐generation EGFR‐TKI osimertinib." (PMID 33131198, 2021). "Overexpression of the EGFR can lead to a poor prognosis, drug tolerance, tumor metastasis, and a low survival rate." (PMID 34578147, 2021). "In the current study, nevertheless, the correlation of LncRNA H19 SNP rs217727 and rs2107425 to the tumor progression of LADC with EGFR wild-type has been observed which is a preliminary experience for this field." (PMID 33799753, 2021). "Emergent cytotoxic activity of EGF in its nanoparticle conjugates is considered as an alternative cancer therapeutics, which conventional EGFR inhibitors have been hampered by the development of drug resistance in some tumor types." (PMID 34512175, 2021). "The upregulation of lnc-EGFR in Tregs was positively correlated with tumor size and EGFR/Foxp3 expression." (PMID 34295338, 2021). "For example myeloid cells support immune evasion in cancer through EGFR/MAPK-dependent regulation of PD-L1 expression in tumor cells." (PMID 33499163, 2021). "As reported, only about half of the patients with acquired resistance to first or second‐generation EGFR‐TKIs can accept re‐biopsy, and 30% of the re‐biopsied tumor tissues were found to be insufficient for downstream genotyping." (PMID 33932095, 2021). "β1 integrin was indeed reported to promote the endocytic machinery of EGFR in cancer cells while LRP-1 was identified as a trigger for β1-integrin intracellular trafficking in the tumour context." (PMID 34831480, 2021). "In xenograft models, human EGFR-targeted NIR-PIT greatly inhibits tumour growth and prolongs survival compared with EGFR mAb monotherapy in various types of cancer cells." (PMID 34332294, 2021). "Aspirin reduces CRC growth via different mechanisms such as, inhibition of cyclooxygenase-2, dysregulation of NFκβ and Wnt-β-catenin signalling pathways, activation of EGFR pathway, host immune response modulation and up-regulation of tumour suppression genes." (PMID 33465114, 2021). "In tumours with high EGFR expression, significantly higher uptake of radiolabelled cetuximab was visually and semi-quantitatively observed compared to tumours with medium or low EGFR expression levels." (PMID 34332294, 2021). "Epidermal growth factor receptor (EGFR) promotes tumor growth by activating proto-oncogenes following phosphorylation." (PMID 33925065, 2021). "The approach to EGFR targeting in each cancer thus depends on the type of EGFR dysregulation specific to each tumour type." (PMID 34069119, 2021). "EGFR protein expression levels increase with tumor stage and were highly correlated with hormone refractory status." (PMID 34321039, 2021). "Autocrine signaling has been demonstrated to maintain cancer stem cells and also activate EGFR in tumour cells." (PMID 34867402, 2021). "In GBM where angiogenesis is thought to be the hallmark of pathogenesis and VEGF its main driver, combining VEGF/EGFR with RT has been shown to halt the growth of glioma cells preclinically and to have a significant synergistic anti-tumor effect with RT." (PMID 34733787, 2021). "Both DWT-Energy and Gabor-Energy decreased from EGFR-mutant group to EGFR-wildtype group, indicating that EGFR mutant tumors were more heterogenous than EGFR wildtype tumor." (PMID 33681463, 2021). "Using cBioPortal, the biological relevance of EGFR alteration in tumor patients derived from the TCGA Pan-cancer datasets was determined." (PMID 33959491, 2021). "For example, reovirus only targets the epidermal growth factor receptor (EGFR) overexpressed cells and replicates in Ras‐activated tumor cells." (PMID 34332576, 2021). "A study with HNSCC cell lines demonstrated beneficial effect of mTOR inhibitors plus cetuximab in the treatment of tumor with low EGFR expression or those that acquired resistance due to cetuximab/cisplatin." (PMID 34490084, 2021).
tumor (continued). "In the phase Ib TATTON trial, 64% of patients with EGFR mutation-positive NSCLC and MET-amplified tumours (MET/CEP7 ratio ≥ 2 or mean GCN ≥ 5) progressing on first-generation EGFR TKI responded to savolitinib plus osimertinib." (PMID 34898564, 2021). "Elevated expression of NRG2 (a ligand of HER/ERBB receptor for activating the EGFR pathway) was found to be correlated with increased tumor aggressiveness." (PMID 34571936, 2021). "On the other hand, anti-EGFR agents improved PFS in KRAS wild type tumor affected patients: cetuximab in combination with FOLFIRI and panitumumab with FOLFOX led to an increase of PFS up to 9,9 and 10 months, respectively." (PMID 33613849, 2021). "Similar to our findings in primary UC tumor samples, EGFR and ERbB2 phosphorylation was observed in all cell lines." (PMID 34600548, 2021). "Cell proliferation and tumor growth were strongly inhibited by biguanide phenformin via targeting of mitochondrial OXPHOS complex 1 in EGFR-TKI-resistant NSCLC cells." (PMID 34367462, 2021). "EphA2 has a clear impact on NSCLC signaling and influences targeted treatment responses including those elicited upon EGFR-TKI treatment or when targeting VEGFR2 expression on tumor cells." (PMID 33671073, 2021). "Tumor cells expressed relatively high levels of EGFR, FGFR1, and FGFR2, while their corresponding ligands, such as COPA, GRN, HBEGF, FGF2, FGF7, and FGF18, were widely expressed in fibroblast cells." (PMID 34459128, 2021). "GPER/EGFR/ERK signaling triggered by GPER specific agonist G1 played a crucial role in decreasing the tumor viability of HCC, both in vitro and in vivo." (PMID 35096574, 2021). "Western blot analyses showed that infigratinib-resistant HCC21-0208, HCC06-0606, and HCC01-0909 tumours constitutively express higher levels of p-EGFR, p-ErbB2, and p-ErbB3." (PMID 34156519, 2021). "EGFR expression has been related to several downstream pathways, prompting a high tumor proliferation rate, hindrance of apoptosis, improved tumor invasion, and metastasis." (PMID 34298758, 2021). "It has been reported that activated EGFR signaling in NSCLC cells can utilize multiple strategies to create an immunosuppressive tumor microenvironment (TME)." (PMID 33537094, 2021). "Even for EGFR- inhibitor therapy a study comparing cetuximab treated patients with low or high miR-31 concentration in tumor tissue found that a low miR-31 expression leads to longer OS and PFS." (PMID 34012511, 2021). "Conversely, the low tumour expression of ER-β was associated with the lower expression of IGF-IR, EGFR, and Ki-67." (PMID 35011656, 2021). "For example, elevated expression levels of epidermal growth factor receptor (EGFR) are related to tumor malignancy and drug resistance." (PMID 34638240, 2021). "They tied the favorable response of the NSCLC patients with uncommon EGFR mutations to the high incidence of concomitant PD-L1 expression and CD8+ tumor-infiltrating lymphocytes within TME." (PMID 34113560, 2021). "It is well known that the EGFR-pathway is a frequently dysregulated system in human cancers, aiding tumor growth, progression, and drug resistance." (PMID 34439289, 2021). "Cetuximab, an anti-epidermal growth factor receptor (EGFR) monoclonal antibody, is an efficient anti-tumor therapeutic agent that inhibits the activation of EGFR; however, data related to the cellular effects of prolonged cetuximab treatment are limited." (PMID 33664437, 2021). "An in vitro study demonstrated that EGFR S645C can promote tumor formation and is less sensitive to erlotinib." (PMID 34660287, 2021). "Strategies to remodel the tumour microenvironment are part of a larger goal to increase the efficiency of anti-EGFR mAbs." (PMID 34663410, 2021).
tumor (continued). "A strategy using combinations of non-competitive anti-EGFR antibodies has been suggested to achieve robust degradation of EGFR, leading to tumor inhibition." (PMID 34207383, 2021). "We will then review the targeted approaches using EGFR inhibitors prior to discussing the more recent immunotherapeutics that have shown good tumor responses in this often-lethal disease." (PMID 34877077, 2021). "Endocytosis inhibitors such as PCZ and Dyngo 4A have been proven to up-regulate tumor antigens such as EGFR and Her2, thereby enhancing ADCC." (PMID 34070311, 2021). "The anticancer effect of this combination was confirmed in a TNBC xenograft model with decreases in CDC42 and p-EGFR (Y1068) in the xenograft tumor." (PMID 34207383, 2021). "The outcomes indicated that Au-IONPs nanoprobe provided significant specificity and high sensitivity for both PET and MRI imaging in the human EGFR-expressing tumor cells." (PMID 34322025, 2021). "We next tested the effects of αEGFR-E-P125A on tumor metastasis using the highly metastatic lung-tropic MDA-MB-231 variant line, MDA-MB-231-4175,with lower but detectable levels of EGFR expression and a high proclivity to form lung metastases." (PMID 34831127, 2021). "The recent findings about the influence of intratumor heterogeneity on the responsiveness of tumor to EGFR TKIs were intriguing." (PMID 33461557, 2021). "The aim of this study was to investigate the irradiation effect on IFNγ-mediated STAT1 and STAT3 phosphorylation and genes expression such as PD-L1 and anti-apoptosis genes in EGFR-positive tumor cells to augment CD8+ T cells cytotoxicity against NSCLC." (PMID 34685495, 2021). "Although the treatment of EGFR-mutant tumors with first- and second-generation TKIs improves tumor control, resistance to first- and second-generation EGFR-TKIs usually occurs within 9–14 months." (PMID 34630120, 2021). "Encouragingly, combination treatment with MEK and EGFR inhibitors seems to be a possible strategy to overcome the multifaceted clonal heterogeneity in tumours." (PMID 34663410, 2021). "It recognizes the m6A modification site in the 3’ UTR of Epidermal growth factor receptor (EGFR) mRNA, promotes its degradation, and plays an anti-tumor role." (PMID 33692959, 2021). "It has been reported that EGFR overexpression can be detected in up to 90% of PC tumour tissues, and that overexpressed EGFR is closely involved in the progression of PC and the poor prognosis of PC patients." (PMID 34809653, 2021). "We identified a new antibody clone (LA1) against epidermal growth factor receptor (EGFR) that successfully abolished tumor cell cluster formation." (PMID 33995681, 2021). "In our tumor banks, we found that the protein expression of EGFR was elevated in GBM samples, whereas LanCL2 expression did not significantly change." (PMID 34461927, 2021). "All these findings strongly suggested that the inhibition of the EGFR not only targeted the tumour cells themselves, but potentially had some influence on tumour-specific immune responses." (PMID 35052732, 2021). "Notch3 silencing in TKI-resistant TNBC cells induces EGFR dephosphorylation and promotes its intracellular arrest, which increases tumor cell sensitivity to TKI–gefitinib treatment." (PMID 34195229, 2021). "In a single-arm phase 2 study, 41 patients aged ≥70 years with untreated mCRC with positive tumour tissue immunohistochemistry for EGFR were treated with single-agent cetuximab." (PMID 34407800, 2021). "The grain-count was higher in the EGFR-positive hypoxic area than in the EGFR-negative non-tumor tissue area." (PMID 33994540, 2021).
tumor (continued). "Conversely, the higher rate of co-occurrent alterations, either “passengers” or even “drivers”, in MET, KRAS, BRAF and EGFR-driven tumors, suggests a branched clonal evolutionary process existing from the early steps of tumor progression." (PMID 33946519, 2021). "The epidermal growth factor receptor (EGFR) is a transmembrane growth factor receptor protein, which directs the behaviour of epithelial cells and tumour cells of epithelial origin." (PMID 34943184, 2021). "An important novel finding in the current study is the identification of two EGFR mutations, EGFRvIII and EGFRvIV, accompanied by amplification in two AA ESCC tumor samples." (PMID 34285259, 2021). "Again, these multicellular spheroids have proven useful to determine the sensitivity of tumor cells to chemotherapeutic drugs or to analyze the diffusion and distribution of the anti-EGFR antibody cetuximab." (PMID 34276690, 2021). "The results of immunohistochemistry (IHC) the tumour was positive (e); the ARMS method (f) identified EGFR mutations in exons 19 and 20 in the tumour." (PMID 33707479, 2021). "DT enzymatic activity was required for tumor regression, and mutant EGFR-expressing tumor cells were the primary target of DT toxicity." (PMID 34494649, 2021). "In these 76 patients, genomic profiling of 128 tumors by MSK-IMPACT yielded a median of 8 somatic alterations per tumor (range, 1–47), and a major oncogenic driver alteration (e.g., EGFR, KRAS, ALK, ROS1, or MET exon 14) was identified in 107 tumors (84%)." (PMID 34359558, 2021). "H460 and H1299 cells are epidermal growth factor receptor (EGFR) wild‐type cells and we further determined the role of USP35 on cell growth, ferroptosis induction, and tumor growth in EGFR mutated H1650 cells." (PMID 33931967, 2021). "Previous studies have established that mutations in EGFR result in its overexpression, while genomic mutations in PTEN tumour suppressor leads to its down‐regulation in GBM." (PMID 33528916, 2021). "Recently, numerous EGFR antibodies and inhibitors have shown substantial application potential in tumor therapy." (PMID 33980265, 2021). "For example, bispecific epidermal growth factor receptor (EGFR)-human epidermal growth factor receptor 2 (HER2) amR-T has exhibited significant anti-tumor efficacy in mouse models." (PMID 33921581, 2021). "Support for such a role of EGFR overexpression comes from publications showing that EGFR inhibitors leads to the rapid tumour cell death in cell culture, as well as in mouse models and data from cancer patients." (PMID 35052732, 2021). "Osimertinib’s irreversible binding to EGFR, and potentially antineoplastic effects in curtailing tumor cell proliferation and tumor vascularization, should be further explored." (PMID 34439273, 2021). "Although GPCR-mediated EGFR transactivation was identified as a crucial mechanism in modulating a variety of tumor cell signaling and functions (Köse, 2017), therapeutic potentials of GPCRs have been rarely probed in EGFR-TKI resistance." (PMID 33967759, 2021). "Nevertheless, littler is known about the role of miRNAs in regulating tumor immune microenvironment and thus affecting anti-EGFR drugs resistance in CRC." (PMID 35111681, 2021). "TFAP2C upregulates the GPX4 gene in tumor cells and regulates some ferroptosis regulators, such as epidermal growth factor receptor (EGFR), CDKN1A, and YAP1, thereby negatively regulating ferroptosis." (PMID 34804126, 2021). "Overall, the EV‐RNA‐based EGFR analysis revealed a complex tumor heterogeneity dynamic with unprecedented resolution, implicating it as a potential clinical decision‐supporting tool." (PMID 33942501, 2021). "High SGLT1 expression mediates enhanced glucose uptake and lactic acid secretion, promoting M2-like TAM polarization and feedback activation of EGFR/PI3K/Akt/SGLT1 signaling in tumor cells to enhance tamoxifen resistance." (PMID 34006822, 2021).